MT1E (metallothionein 1E)
Diseases named in the same sentence as MT1E in open-access papers:
MT1E is named in the same sentence as 45 diseases in open-access papers, as found by Europe PMC text mining. Sharing a sentence is not in itself a finding about the gene and the disease. The quoted sentences say what the papers report.
glioma (8 papers, 2015 to 2024). A benign or malignant brain and spinal cord tumor that arises from glial cells (astrocytes, oligodendrocytes, ependymal cells). "For example, STAT3 upregulated the expression of MT1E, the gene encoding metallotheonine-1E, which enhances human glioma cell migration and invasion by inducing the inactivation of MMP-9." (PMID 29774125, 2018). "The co-expressed genes, MT1E and MT1H, were previously associated with tumour invasion in bladder, glioma, liver and prostate cancer respectively." (PMID 32636408, 2020). "For example, it has been demonstrated that MT1E expression correlates positively with the invasive and migratory abilities of glioma cells." (PMID 25933064, 2015). "However, MT1E expression in glioma was able to promote the migration and invasion effects of glioma." (PMID 38951569, 2024). "Another member, MT1E, could modulate the motility and invasion of a human glioma cell line by upregulating MMP9 as well, and this interaction was also related to an association between MT1E and NF-κB." (PMID 28109307, 2017). "The analysis of MT1A, MT1E, MT1X, MT2, MT3 gene mRNA expression was determined in n = 51, n = 53, n = 49, n = 55, n = 51 glioma patients respectively." (PMID 30932010, 2019). "Here we checked MT1A, MT1E, MT1X, MT2, MT3 gene expression level and epigenetic regulation for one of the highly expressed metallothioneins, MT1A, in different grade gliomas and looked for clinical significance of MT gene activity in glioma tissue in terms of patient survival." (PMID 30932010, 2019).
malignant melanoma (6 papers, 2013 to 2025). "MT1E promoter hypermethylation was previously reported only in melanoma and endometrial cancer patients, but, to the best of our knowledge, has never been assessed in PCa." (PMID 28977898, 2017). "MT1E is methylated in malignant melanoma and increases sensitivity to cisplatin-induced apoptosis." (PMID 40495885, 2025). "Previous studies have indicated that MT1E, MT1F and MT1M are antitumor genes in malignant melanoma, colon carcinoma cells, and hepatocellular carcinoma HepB3, respectively." (PMID 36009228, 2022). "Thus, while known targets of CPEB4 such as the metallothionein proteins MT2A and MT1E were found in both cell types, 93% of the CPEB4-bound transcripts in melanoma (that is, 312/331) had not been reported in RWP1." (PMID 27857118, 2016).
prostate carcinoma (6 papers, 2017 to 2025). A carcinoma that arises from epithelial cells of the prostate gland. "MT1E has been implicated in various cancers, with studies revealing its downregulation and potential role in liver and prostate cancer." (PMID 39979869, 2025). "Studies have shown that decreased expression of MT1E promotes the progression of prostate cancer." (PMID 38441550, 2024). "The results suggested that MT1E downregulation was a potential biomarker of early BCR and poor prognosis in prostate cancer patients." (PMID 30139373, 2018). "They identified 455 differentially expressed genes through global gene expression profiling, among which seven genes (CHI3L2, FABP7, GHRH, GPR52, MT1E, OLR1, and SAA2) were selected for further validation in two independent prostate cancer cohorts." (PMID 30139373, 2018).
breast carcinoma (4 papers, 2011 to 2024). "Further, the MT1E c.G107A mutation may downregulate the expression of MT1E, potentially contributing to the development of breast cancer." (PMID 39138583, 2024). "The induction of GAGE gene expression by the MT1E isoform is interesting since there is some evidence that the expression of MT1E is altered in breast cancer and breast cancer cell lines." (PMID 28545470, 2017). "The analysis revealed a significant downregulation of MT1E in breast cancer tissues." (PMID 39138583, 2024). "Additionally, compared with breast cancer tissues, the expression of MT1E is higher in the para-cancer tissues, which indicates that MT1E may play an important role as a tumor suppressor gene." (PMID 39138583, 2024). "In further investigations, four breast cancer cell lines were screened for mRNA expression of MT1F, MT1E, SLC30A1, and S100P after treatment with BA or CAI3 and showed an upregulation of MT1F, MT1E, SLC30A1, and S100P in four breast cancer cell lines." (PMID 39594441, 2024). "The differential effect of MT3 and MT1E on the expression of GAGE genes suggests unique roles of these genes in the development and progression of breast cancer." (PMID 28545470, 2017). "The differential effects of MT3 and metallothionein 1E on the expression of GAGE genes suggests unique roles of these genes in the development and progression of breast cancer." (PMID 28545470, 2017). "Evidence that this finding might translate to human specimens of breast cancer tumors is provided by a study on a series of fresh breast cancers which showed that the MT1E isoform was highly expressed in estrogen receptor negative compared to estrogen receptor positive breast cancers." (PMID 28545470, 2017).
hepatocellular carcinoma (4 papers, 2022 to 2024). A malignant tumor that arises from hepatocytes. "Overexpression of MT1E in hepatocellular carcinoma cells resulted in a significant decrease in both cell viability and cell number." (PMID 39061894, 2024). "For example, MT1E expression is downregulated in hepatocellular carcinoma (HCC), and MT1E induces apoptosis of HCC cells and inhibits metastasis." (PMID 35642057, 2022). "Genes like MT1E and MT1F can be used as biomarkers to predict the recurrence of hepatocellular carcinoma." (PMID 39061894, 2024).
Alzheimer disease (2 papers, 2020 to 2023). A progressive, neurodegenerative disease characterized by loss of function and death of nerve cells in several areas of the brain leading to loss of cognitive function such as memory and language. "Mathys and colleagues investigated the frontal cortex of human late onset Alzheimer disease using snRNAseq and showed expression of MT2A, MT1G, and MT1E in astrocytic cluster Ast1." (PMID 32070434, 2020).
endometrial cancer (2 papers, 2010 to 2017). Primary or metastatic malignant neoplasm involving the endometrium (mucous membrane that lines the endometrial cavity). "Promoter hypermethylation of RASSF1A, metallothionein 1E, and related tumor-suppressor genes have been found to correlate with clinicopathological parameters in endometrial cancer." (PMID 20814443, 2010).
esophageal cancer (2 papers, 2022 to 2023). A primary or metastatic malignant neoplasm involving the esophagus. "MT1E is an isoform of MT1, and it has been reported that MT1E expression is positively correlated with esophageal cancer malignancy." (PMID 36761024, 2023). "MT2A, MT1E, MT1X expression is associated with CD8+ T cell infiltration in malignant tumors including esophageal cancer." (PMID 36466860, 2022). "TCGA database was used to analyze the relationship between expression of MTA2, MT1E and MT1X in esophageal cancer and prognosis and survival, and the analysis results showed that low expression of MT2A, MT1E and MT1X was associated with poorer overall survival." (PMID 36466860, 2022). "GEPIA database analysis, MT1E, MT1X molecule transcription levels in esophageal cancer patients and normal control group MT2A, MT1E, MT1X molecule." (PMID 36466860, 2022). "The expression of MT2A, MT1E and MT1X in esophageal cancer patients and normal persons was detected by TCGA database, and it was found that the expression of MT2A, MT1E and MT1X in esophageal cancer patients was significantly reduced." (PMID 36466860, 2022). "The expression of MT2A, MT1E and MT1X in esophageal carcinoma and their relationship with CD8+ T cell infiltration were detected." (PMID 36466860, 2022). "The expression of MT2A, MT1E and MT1X in esophageal cancer patients and normal controls was detected by TCGA database, and it was found that the expression of MT2A, MT1E and MT1X in esophageal cancer patients was significantly reduced, which was associated with poor prognosis." (PMID 36466860, 2022).
periodontal disease (2 papers, 2019 to 2022). "The present validation study confirmed that the genes for the MT1F, MT1X, MT1M, MT1E, and MT2A isoforms exhibit a statistically significant alteration of expression in Down’s syndrome patients with active periodontal disease and implant failure." (PMID 35741790, 2022).
psychosis (2 papers, 2008 to 2023). "Using a quantitative PCR, we validated a set of genes such as up-regulated metallothioneins (MT1E, MT1F, MT1H, MT1K, MT1X, MT2A and MT3) and down-regulated neuropeptides (SST, TAC1 and NPY) in the dorsolateral prefrontal cortex of psychosis patients." (PMID 18992145, 2008). "In the current cross-study analysis, we identified a set of metallothionein genes including MT1X, MT1K, MT1E, MT1H, MT1F, MT2A and MT3 that are significantly up-regulated in psychosis." (PMID 18992145, 2008). "In a study conducted on postmortem subjects with and without psychosis, up-regulation in MT1E, MT1F, MT1H, MT1K, MT1X, MT2A, and MT3 genes was observed in the dorsolateral prefrontal cortex." (PMID 36831126, 2023).
aneurysm (1 paper, 2021). Bulging or ballooning in an area of an artery secondary to arterial wall weakening. "This implies, among others, that MT1E may be involved in induction of matrix metalloproteinases, which is observed during aneurysm formation." (PMID 34827608, 2021).
astrocytomas (1 paper, 2019). "MT1A, MT1E, MT1X, MT2, MT3 gene expression was elevated in grade IV astrocytomas (glioblastomas) as compared to astrocytomas grade I-III." (PMID 30932010, 2019). "Analysis showed the trend for increasing MT1A, MT1E, MT1X, MT2 and MT3 gene expression in higher malignancy tumours, e.g. glioblastomas as compared to I-III grade astrocytomas." (PMID 30932010, 2019).
Cachexia (1 paper, 2022). Severe weight loss, wasting of muscle, loss of appetite, and general debility related to a chronic disease. "In addition, consistent with higher percentage of effector-memory CD8+ T cells in non-cachexia patients, genes relevant to the dysfunctional phenotype and the state of inactivation such as MT1X, MT1E, IL7R, and ZFP36L2 were highly expressed in CD8+ T cells in non-cachexia patients." (PMID 36376273, 2022).
colorectal tumor (1 paper, 2022). "We note that four genes (SAT1, MT1E, HSP90AA1, and HNRNPH1) from a colorectal tumor tissue have interactions with HIV-1 proteins." (PMID 36290397, 2022).
COVID-19 (1 paper, 2023). A disease caused by infection with severe acute respiratory syndrome coronavirus 2. "Interestingly, we found metal ion homeostasis pathway associated with metallothionein (MT2A, MT1E, and MT1X) genes enriched within CD8+ TCM, CD8+ TEM, and activated CD4+ T cells in the COVID-19 positive individuals." (PMID 37886355, 2023).
esophageal squamous cell carcinoma (1 paper, 2022). Esophageal squamous cell carcinoma (ESCC) is a type of esophageal carcinoma (EC) that can affect any part of the esophagus, but is usually located in the upper or middle third. "Therefore, MT2A, MT1E, MT1X may be potential predictors of anti-PD-1 therapy in patients with advanced esophageal squamous cell carcinoma." (PMID 36466860, 2022).
glioblastoma (1 paper, 2019). The most malignant astrocytic tumor (WHO grade IV). "However, only MT1A and MT2 expression reached a statistically significant level (Mann-Whitney test, p < 0.05), while MT1E and MT3 genes showed the tendency of higher expression in glioblastomas (Mann-Whitney test, p = 0.120, p = 0.058 respectively)." (PMID 30932010, 2019).
Hepatic steatosis (1 paper, 2025). Steatosis is a term used to denote lipid accumulation within hepatocytes. "Group studying mutations in the MT1E gene in a three-generation family with diabetes found that carriers of the MT1E p.C36Y mutation demonstrated increased weight gain, elevated postchallenge serum glucose, elevated liver enzyme levels, and hepatic steatosis." (PMID 40755507, 2025).
liver cancer (1 paper, 2021). An epithelial or non-epithelial malignant neoplasm that arises from the liver. "Our analysis disclosed that MT1E was downregulated in liver cancer and may serve a similar function as MT1M." (PMID 34423049, 2021). "However, the role of MT1E in liver cancer is seldom studied." (PMID 34423049, 2021).
lung carcinoma (1 paper, 2012). "Hypermethylation and/or the downregulation of some of the genes identified in our study (e.g. ALDH1A2, HOXA5, MT1E, SOX17) have been reported in other cancers, but not yet in lung cancer." (PMID 22768131, 2012).
mastitis (1 paper, 2024). Inflammation of breast tissue during lactation or postpartum due to an obstructed duct or infection. "Similarly, the expression of genes related to lactation and other mammary traits (SLC38A2, SLC35B1), fertility (SLC38A2, MT1E), susceptibility to paratuberculosis, mastitis and trypanosomiasis (IL6), and feed intake/efficiency (MT1E, SLC38A2) was upregulated in Mirandesa cattle." (PMID 39333243, 2024).
schizophrenia (1 paper, 2017). A major psychotic disorder characterized by abnormalities in the perception or expression of reality. "The paralogous genes of GBP1, MT2A and APOL1, including GBP2, MT1G, MT1E, MT1F, MT1L and APOLD1, were also upregulated in the schizophrenia cases." (PMID 28809853, 2017).
tuberculosis (1 paper, 2024). A chronic, recurrent infection caused by the bacterium Mycobacterium tuberculosis. "In contrast, the upregulated genes in perirenal adipose tissue of Mirandesa cattle, such as CD209 and MT1E, suggest adaptations related to tuberculosis susceptibility and postpartum oxidative stress, respectively." (PMID 39333243, 2024).
uterine cancer (1 paper, 2025). Primary or metastatic malignant neoplasm involving the uterine corpus and/or the cervix. "The reduction in MT1E expression in uterine cancer may further contribute to the progression and severity of the disease." (PMID 39979869, 2025).
viral infection (1 paper, 2020). "The top-scoring genes in the network include the members of Interferon Induced Transmembrane Proteins (IFITM1 and IFITM3) followed by MT1E, MT1X, and MT1G and OASL, all essential proteins involved in the innate immune response to viral infection." (PMID 32012164, 2020).
tumor (25 papers, 2013 to 2025). "In our study, we similarly identified MT1E as a tumor suppressor, further supporting its role in regulating cell motility, migration, and cancer metastasis." (PMID 40386382, 2025). "MT1E has been identified as a tumor suppressor, with its methylation correlating with HCC metastasis." (PMID 41050411, 2025). "Genetically, CRISPR screening identified that the loss of genes such as MT1E and S100A4 promotes tumor cell migration." (PMID 41142598, 2025). "The over-expression of MT1E was found to enhance sensitivity to cisplatin-induced apoptosis, thereby suggesting its potential as a tumor suppressor gene." (PMID 37705737, 2023). "Analysis of associations between biomarkers and tumor grading revealed statistically significant differences in promoter hypermethylation of RASSF1, ADAMTS12 (G1 vs. G2), and MT1E (G2 vs. G3) (p < 0.05)." (PMID 36499753, 2022). "Additionally, xenograft mouse models revealed MT1E as a novel tumor suppressor, inhibiting migration and invasion and inducing apoptosis." (PMID 40386382, 2025). "Since apoptosis was a crucial mechanism through which cetuximab induced tumor cell death 30, MT1E and MT2A expression might correlate with enhanced drug sensitivity, while PCK1 and TGFBI expression might be linked to resistance." (PMID 40959565, 2025). "MT1E was newly identified as a novel tumor suppressor for HCC that could induce apoptosis and suppress cell growth and metastasis." (PMID 35300417, 2022). "RUNX3 encodes a tumor suppressor which regulates cell growth, survival, differentiation, angiogenesis, and invasion; FILIP1L is a protein that inhibits metastases and chemoresistance; MT1E is a cytoskeleton-modifying protein, involved in cell migration and invasion." (PMID 36499753, 2022). "Besides, MT1E down-regulation was predominant in the cases with early BCR and showed associations with clinical markers of poor prognosis, i.e. higher grade group and more advanced tumor stage." (PMID 28977898, 2017). "In contrast, BTG2, MT1E, and PHYHD1 were identified as protective factors in our model, potentially functioning as suppressors of tumor progression." (PMID 40496864, 2025). "Cluster Fib_6 cells exhibited high expression of MT1-related genes (MT1E and MT1X) that activate tumor-suppressing immune cells." (PMID 37533434, 2023). "Four genes from the metallothionein cluster on human chromosome 16q13 (MT1A, MT1E, MT1M, MT2A) were overexpressed in 231_HM.LNm5 tumours only, thus placing them in the metastatic virulence category." (PMID 29720474, 2018). "This may partially explain why knocking out SEMA6B, MT1E, S100A4, or ASAH2 may significantly promote tumor colony growth." (PMID 39605490, 2024). "Therefore, the four MT1s (MT1G, MT1E, MT1F and MT1X) are down regulated in tumor samples, at the same time, they are also down regulated in tumor samples with MT1 deletion, indicating that MT1 deletion may affect the expression of its genes in HCC." (PMID 34257549, 2021).
cancer (11 papers, 2012 to 2025). A tumor composed of atypical neoplastic, often pleomorphic cells that invade other tissues. "MT1E has been implicated in migration and invasion within cancer cell lines, and its concordance with mesenchymal cell populations is further supported by this cell type characterized with higher invasiveness." (PMID 36598637, 2023). "Several metallothionein genes, including MT1E, MT1G and MT1M were upregulated in the SPINK1 general cancer pathway." (PMID 35369880, 2022). "Next, the correlation between MT2A, MT1E, MT1X expression and CD8+ T cells and other immune cells in various malignant tumors was analyzed by bioinformatics database." (PMID 36466860, 2022). "Strikingly, members of the metallothionein family, including MT1M, MT1H, MT1G, MT1F, MT1E, MT1X, and MT1A, were significantly downregulated in cancer cells." (PMID 35967424, 2022). "A majority of cuproptosis-related genes like CP, MT1E, MT1F, MT1X, VEGFA, and PDK1 were expressed significantly higher on cancer cells, indicating that cuproptosis might occur mainly on cancer cells." (PMID 36211378, 2022).
infection (3 papers, 2016 to 2023). The state of being infected such as from the introduction of a foreign agent such as serum, vaccine, antigenic substance or organism. "We validated in two cell-lines (Caco-2 and HT-29) the changes in expression of a number of genes (MT1E, NPPB, NOTCH3, CYP26A1, HEY1 and CYP1A1) found to be differentially expressed using RNAseq following infection with C. concisus UNSWCD or BAA-1457." (PMID 27677841, 2016).
MT1E also shares sentences with these, for which no sentence is quoted: colon carcinoma (2 papers); colorectal cancer (2); acute kidney injury (1); amyloidosis (1); autism (1); bladder cancer (1); cardiac hypertrophy (1); Down syndrome (1); epilepsy (1); kidney diseases (1); malignant glioma (1); metabolic disease (1); mood disorder (1); nasopharyngeal carcinoma (1); nephropathies (1); pancreatic cancer (1); trypanosomiasis (1).